PTPN2 (protein tyrosine phosphatase non-receptor type 2)
Diseases named in the same sentence as PTPN2 in open-access papers (continued):
Sharing a sentence is not in itself a finding about the gene and the disease.
colon cancer (3 papers, 2021 to 2023). "To address this question, we used CRISPR/Cas9 editing to generate stable control (sgNTC) and Ptpn2 KO (sgPtpn2) CT26 and MC38 murine colon cancer cell lines." (PMID 36968224, 2023).
diabetic nephropathy (3 papers, 2018 to 2020). "Multiple stepwise regression analysis and correlation analysis demonstrated that a reduction of PTPN2 is associated with lower VDR and higher uACR, a major indicator for assessing the development of diabetic kidney disease." (PMID 30246029, 2018). "We investigated the expression of PTPN2 in T2DM and its correlation with the severity of diabetic kidney disease, VDR, and inflammatory factors MCP-1, IL-6, and TNFα." (PMID 30246029, 2018).
gastric cancer (3 papers, 2018 to 2022). A primary or metastatic malignant neoplasm involving the stomach. "Furthermore, PTPN1 is implicated in the poor prognosis of gastric cancer, and PTPN2 is linked to the incidence of gastric cancer." (PMID 35957898, 2022).
Hepatic steatosis (3 papers, 2023 to 2025). Steatosis is a term used to denote lipid accumulation within hepatocytes. "When we performed multivariable logistic regression analysis, the MBOAT7 rs641738 C/T+T/T and the PTPN2 rs2542151 G/T+G/G genotypes, as well as serum triglycerides and hepatic steatosis index, were the independent predictors of MASLD susceptibility." (PMID 41019340, 2025). "Multivariable regression analysis revealed that triglycerides, hepatic steatosis index, MBOAT7 rs641738 (C/T+T/T), and PTPN2 rs2542151 (G/T+G/G) were independent predictors of MASLD susceptibility." (PMID 41019340, 2025).
leukemia (3 papers, 2017 to 2023). A malignant (clonal) hematologic disorder, involving hematopoietic stem cells and characterized by the presence of primitive or atypical myeloid or lymphoid cells in the bone marrow and the blood. "Among them, Nelarabine and Fludarabine can have certain curative effect on leukemia, suggesting that PTPN2 is closely correlated to drug resistance in patients with hematologic tumors." (PMID 37884566, 2023). "Among them, mercaptopurine was often used as a therapeutic agent for leukemia, indicating that the correlation between PTPN2 and hematological cancers was robust." (PMID 37884566, 2023).
periodontitis (3 papers, 2019 to 2024). An acute or chronic inflammatory process that affects the tissues that surround and support the teeth. "PTPN2 expression was increased in both periodontitis groups but was more pronounced in the DP group, particularly in the connective tissue." (PMID 38241313, 2024).
squamous carcinoma (3 papers, 2017 to 2025). "PTPN2 is inversely correlated with the grade of squamous cell carcinoma." (PMID 36077422, 2022).
triple-negative breast carcinoma (3 papers, 2018 to 2023). An invasive breast carcinoma which is negative for expression of estrogen receptor (ER), progesterone receptor (PR), and human epidermal growth factor receptor 2 (HER2). "Furthermore, loss of PTPN2 in patients with triple-negative breast cancer was associated with poor response to tamoxifen demonstrating the relevance of this phosphatase to the response of human cancer to chemotherapy in addition to immunotherapy." (PMID 36968224, 2023). "These preclinical findings appear to be relevant to human tumors, since low PTPN2 protein in triple-negative breast cancer (TNBC) is accompanied with TILs/T cells and increased PD-L1 levels, whereas low PTPN2 mRNA is associated with improved survival." (PMID 37500611, 2023).
viral infection (3 papers, 2019 to 2023). "We use this approach to perform an in vivo pooled genetic screen and identify Ptpn2 as a negative regulator of CD8+ T cell-mediated responses to LCMV Clone 13 viral infection." (PMID 30971695, 2019). "Indeed, previous studies showed that beta cells without PTPN2 expression have impaired function and displayed increased levels of apoptosis upon stress exposure, including mimicking viral infections and transplantation." (PMID 36497105, 2022).
clear cell renal cell carcinoma (2 papers, 2018 to 2023). "Overexpression of PTPN2 also predicted a poor survival in clear cell renal cell carcinoma, which agrees with our results." (PMID 37509645, 2023).
COVID-19 (2 papers, 2024 to 2025). A disease caused by infection with severe acute respiratory syndrome coronavirus 2. "Here, we demonstrate that the IBD risk SNP rs1893217 in PTPN2 is associated with increased expression of ACE2 and SARS-CoV-2 entry and might represent a novel COVID-19 genetic susceptibility biomarker." (PMID 39756517, 2025).
lymphoma (2 papers, 2018 to 2025). A malignant (clonal) proliferation of B- lymphocytes or T- lymphocytes which involves the lymph nodes, bone marrow and/or extranodal sites. "Further studies are needed to determine the role of PTPN2 in PTCLs and whether loss of this phosphatase can induce a central tolerance checkpoint in lymphoma cells." (PMID 29789628, 2018). "A moderately higher PTPN2 expression was observed in ALK+ ALCL cell lines (SUDHL1 and Karpas299) compared to diffuse large B‐cell lymphoma (DLBCL) cell lines (SUDHL8, FARAGE, and SUDHL4), Burkitt lymphoma (BL) cell line RAJI, and T‐cell leukemia/lymphoma cell lines (JURKAT and MJ)." (PMID 40734623, 2025).
neuroblastoma (2 papers, 2011 to 2021). Neuroblastoma (NB) is the most common solid, extracranial childhood tumor. "Additional PTPN2 substrates related with neuroblastoma cell growth are expected, although the expression of PTPN2 in neuroblastoma cells is poorly documented." (PMID 34957126, 2021). "The possibility exists that ALK and PTPN11 are direct substrates of PTPN1 and PTPN2 in neuroblastoma cells." (PMID 34957126, 2021). "In the present study we explored the possibility of cellular phospho-C3G (pC3G) being a substrate of the intracellular T-cell protein tyrosine phosphatase TC-PTP (PTPN2) using the human neuroblastoma cell line, IMR-32." (PMID 21876762, 2011).
pancreas cancer (2 papers, 2022 to 2025). "The heat map showed that 3,174 genes in PAAD have a negative correlation with the PTPN2 expression, and 3,830 genes have a positive correlation with the expression of PTPN2 in pancreas cancer." (PMID 35154122, 2022).
pericarditis (2 papers, 2014 to 2015). An inflammatory process affecting the pericardium. "Conversely, the SNP rs2542151 of PTPN2 resulted in being associated with serositis, and specifically with pericarditis." (PMID 26798662, 2015). "The study conducted by Ciccacci and colleagues in 2014 identified a new association between the occurrence of pericarditis and the genetic variant rs2542151 of PTPN2 gene (OR = 2.49)." (PMID 26798662, 2015). "For example, PTPN2 SNP resulted associated with a higher risk to develop pericarditis and serositis, while ATG16L1 SNP resulted protective towards pericarditis." (PMID 25369137, 2014).
preeclampsia (2 papers, 2018 to 2024). Preeclampsia is a hypertensive disorder of pregnancy that is characterized by new-onset hypertension with proteinuria presenting after 20 weeks of gestation, and depending on mild or severe forms may initially present with severe headache, visual disturbances, and hyperreflexia. "For example, miR-210 can down regulate PTPN2 mRNA contributing to the pathogenesis of preeclampsia and has a central role in the switch from trophoblast proliferation to an invasive phenotype." (PMID 29293682, 2018). "Conversely, Ptpn2 mRNA expression was shown to be decreased in human placentas from preeclampsia." (PMID 39090270, 2024).
psoriatic arthritis (2 papers, 2016 to 2020). Joint inflammation associated with psoriasis. "No genetic association between PTPN2 and SpAs has emerged so far; however, to the best of our knowledge, GWAS in SpAs have been limited to ankylosing spondylitis and psoriatic arthritis." (PMID 33055428, 2020).
Sepsis (2 papers, 2022 to 2024). Sepsis is defined as life-threatening organ dysfunction caused by a dysregulated host response to infection. "In HK-2 cells (a classical model of sepsis-induced renal injury in vitro), PTPN2 reduced LPS-induced inflammatory cytokine release and cell death via modulating p38 MAPK/NF-κB signaling, which alleviated renal cell damage by playing a nephron-protective role in sepsis-induced renal injury." (PMID 36077422, 2022).
thyroid cancer (2 papers, 2022). "PTPN2 is also upregulated in thyroid cancer tissues and cell lines, especially in metastatic subtypes." (PMID 36077422, 2022).
asthma (1 paper, 2016). "In particular to PTPN2, a compound, glycyrrhizin from Glycyrrhiza glabra and Glycyrrhiza uralensis, is supported by an in vivo study that suggests the compound ameliorates all established chronic histopathologic changes of lung tissue in the mouse model of asthma." (PMID 26989424, 2016).
breast tumors (1 paper, 2010). "We have also pointed to other 18p TSG candidates including ZFP161, CEP76, PPP4R1 and PTPN2 whose involvement might explain the aggressive phenotype of breast tumors with 18p loss." (PMID 20698951, 2010).
E. coli infections (1 paper, 2023). "We show that PTPN2 loss in macrophages promotes a strong type 1 immune response, which is necessary to promote clearance of and recovery from infection with Citrobacter rodentium, a mouse pathogen that models human enteropathogenic and enterohemorrhagic E. coli infection." (PMID 36810248, 2023).
Evans syndrome (1 paper, 2025). "Recently, six distinct heterozygous PTPN2 mutations (F403Lfs*25, W98*, C216S, E24Mfs*20, W289*, and Y126N), which result in loss of PTPN2 regulatory function, were reported to associate with patients with Evans syndrome or pediatric-onset systemic lupus." (PMID 39944077, 2025).
gallstones (1 paper, 2021). Solid crystalline precipitates in the biliary tract, usually formed in the gallbladder, resulting in the condition of cholelithiasis. "UC patients carrying the C-allele of the PTPN2 SNP rs1893217 are more likely to have a more severe disease course, including gallstones—which suggests altered bile acid homeostasis." (PMID 34442830, 2021).
Glomerular sclerosis (1 paper, 2019). Accumulation of scar tissue within the glomerulus. "Since overproduction of extracellular matrix is a hallmark of DN and results in glomerular sclerosis and interstitial fibrosis, we next explored whether PTPN2 could ameliorate renal lesions by preventing renal fibrosis." (PMID 30955247, 2019).
HCMV infection (1 paper, 2023). "However, during HCMV infection with a WT and ΔUL138STOP virus, total levels of PTPN2 and activated levels of SHP-2 (phosphorylated at tyrosine 542, pSHP-2) were induced equally between infections at 48 hpi." (PMID 37289831, 2023). "As USP12 has been reported to antagonize PTPN2’s dephosphorylation of pSTAT1, it is also possible that interaction with USP12 contributes to UL138-mediated sustainment of pSTAT1 during HCMV infection." (PMID 37289831, 2023).
intestinal infections (1 paper, 2023). "In summary, our results demonstrate that loss of PTPN2, and subsequently impaired interaction between macrophages and IECs, culminate in an inability to defeat invading pathogens and render the host susceptible to intestinal infections." (PMID 36810248, 2023).
intestinal inflammation (1 paper, 2021). "Therefore, in the present study we aimed to explore the interaction between the food additive TiO2 and the well-characterized IBD risk gene protein tyrosine phosphatase non-receptor type 2 (Ptpn2) and their role in the development of intestinal inflammation." (PMID 33466682, 2021).
iron deficiency (1 paper, 2025). "In the Ptpn2-KO mouse model, the significantly reduced serum iron levels and transferrin saturation are indicative of iron deficiency." (PMID 40244226, 2025). "This may be due to some form of kidney dysfunction, as Ptpn2-deficient mice develop nephritis and the suppression of liver hepcidin expression is likely due to mechanisms related to iron deficiency." (PMID 40244226, 2025). "The lack of 55Fe present in duodenal IECs of Ptpn2-KO mice provides evidence that a contributor to the iron deficiency apparent in these mice might be a defect at the duodenal brush border." (PMID 40244226, 2025).
liver fibrosis (1 paper, 2022). "First, target proteins (PTPN2 and PIM1) that have not been clearly reported to be related to liver fibrosis were excluded." (PMID 35517817, 2022).
liver inflammation (1 paper, 2025). "Recently, partial PTPN2 deletion in dendritic cells was found to be associated with liver inflammation." (PMID 41019340, 2025).
lung fibrosis (1 paper, 2020). "We were unable to find any reports linking either PTPN2 to silicosis, and it has been reported that IL-6 family of cytokines, which signal through STAT-3, may contribute to lung fibrosis." (PMID 32054021, 2020).
lymphopenia (1 paper, 2015). Reduction in the number of lymphocytes. "In this regard, PTPN2 limits lymphopenia-induced proliferation in conventional T-cells." (PMID 26815406, 2015).
metastatic melanoma (1 paper, 2025). A melanoma that has spread from its primary site to another anatomic site. "In addition, BIN2, CMTM8, CXCL10, HCLS1, ITGB2, PTPN2, and RFTN2 were expressed at significantly higher levels in our B16 brain-derived variants compared with the parent B16-F0 and are also upregulated in human metastatic melanomas compared with primary cutaneous tumors." (PMID 39819494, 2025).
metastatic tumors (1 paper, 2023). "Phase I trials are currently underway assessing the safety and efficacy of the PTP1B/PTPN2 inhibitors in patients with locally advanced or metastatic tumors (NCT04417465, NCT04777994)." (PMID 37500611, 2023). "At present two PTP1B/PTPN2 inhibitors, ABBV-CLS-484 and ABBV-CLS-579, are in phase I clinical trials (NCT04417465, NCT04777994) for patients with locally advanced or metastatic tumors and are being tested alone and in combination with α-PD-1." (PMID 37500611, 2023).
Myalgia (1 paper, 2025). "However, central in this core net one can find the genes NF2 and BRAF (associated to HPO-class BN and ACTH), EP300 (associated to HPO-class BN), AAAS (associated to HPO-class ACTH) and PTPN2 (associated to Myalgia)." (PMID 40831500, 2025).
non-alcoholic fatty liver disease (1 paper, 2024). "In addition, PTPN2 rs2542151 has been linked to a higher prevalence of type 2 diabetes (T2DM) and greater severity of non-alcoholic fatty liver disease (NAFLD)." (PMID 39682729, 2024).
oligoarticular JIA (1 paper, 2014). "For oligoarticular JIA PTPN2 was the seed gene of importance." (PMID 24886659, 2014).
ovarian serous cystadenocarcinoma (1 paper, 2023). A malignant serous cystic epithelial neoplasm arising from the ovary. "However, low PTPN2 expression was associated with poor overall survival in ovarian serous cystadenocarcinoma, indicating its versatile roles in different cancer types." (PMID 37509645, 2023).
pancreatic ductal adenocarcinoma (1 paper, 2022). An infiltrating adenocarcinoma that arises from the epithelial cells of the pancreas. "Ishikawa dataset showed that in pancreatic ductal adenocarcinoma PTPN2 was increased with a fold change of 1.895 when compared with normal samples." (PMID 35154122, 2022).
periodontal disease (1 paper, 2016). "A recent research implied that the expression of PTPN2 decreased in gingival epithelial under condition of periodontal disease." (PMID 27995146, 2016).
sarcoma (1 paper, 2020). A usually aggressive malignant neoplasm of the soft tissue or bone. "PTPN2‐deficient CD8+ HER‐2 CAR T cells were more activated, as assessed by the expression of CD44, CD25, PD‐1 and LAG‐3, after overnight incubation with HER‐2‐expressing 24JK (24JK‐HER‐2) sarcoma cells, but importantly, not HER‐2‐negative 24JK control cells (Fig EV1B)." (PMID 31803974, 2020).
silicosis (1 paper, 2020). Silicosis is a respiratory disease caused by breathing in (inhaling) silica dust. "Our study showed that PTPN2 concentrations were significantly higher in rat silicosis and SiO2-stimulated MLE-12 cells than in the control groups." (PMID 32054021, 2020). "Our study also showed that PTPN2 can inhibit epithelial-mesenchymal transition by dephosphorylating STAT3 in silicosis fibrosis." (PMID 32054021, 2020). "This information was used to assess whether similar markers were upregulated in SiO2-stimulated murine lung epithelial (MLE)-12 cells, and the mechanism of PTPN2 inhibiting silicosis fibrosis was studied." (PMID 32054021, 2020). "PTPN2 can inhibit EMT by dephosphorylating STAT3 in silicosis fibrosis." (PMID 32054021, 2020). "EMT was closely related to silicosis; therefore, PTPN2 might be the key protein in the process of silicosis." (PMID 32054021, 2020). "We next found that the PTPN2, Factor B, and VRK1 concentrations in silicotic rats silicosis and SiO2-stimulated MLE-12 cells were significantly higher than control groups." (PMID 32054021, 2020). "In conclusion, we found three proteins, PTPN2, factor B, and VRK1, to be significantly upregulated in silicosis." (PMID 32054021, 2020). "This study verified that Protein PTPN2, factor B, and vaccinia-related kinase 1 (VRK1) were significantly upregulated in rat silicosis and SiO2-stimulated MLE-12." (PMID 32054021, 2020).